ENSG00000234352 (novel transcript, antisense to CHRM2)
Synonyms: LOC105375524; LOC349160
Gene: Long non-coding RNA gene on chromosome 7 (136,685,559 to 137,182,107, reverse strand). Ensembl gene ENSG00000234352.
Gene Ontology:
Biological process: miRNA-mediated post-transcriptional gene silencing
Cellular component: RISC complex